Y_RNA (Y RNA )
Gene: Miscellaneous RNA gene on chromosome 22 (50,669,804 to 50,669,901, forward strand). Ensembl gene ENSG00000212569.
Homologues: Orthologues: chimpanzee Y_RNA (94% identical), macaque Y_RNA (93% identical). Paralogues in human: Y_RNA (87% identical), RNY3 (86% identical), Y_RNA (86% identical), Y_RNA (85% identical), Y_RNA (84% identical), RNY3P1 (83% identical), RNY3P14 (83% identical), Y_RNA (83% identical), RNY3P5 (82% identical), Y_RNA (82% identical), RNY3P16 (81% identical), Y_RNA (81% identical), and 93 more.